MTMR6 (myotubularin related protein 6)
Description:
Lipid phosphatase that specifically dephosphorylates the D-3 position of phosphatidylinositol 3-phosphate and phosphatidylinositol 3,5-bisphosphate, generating phosphatidylinositol and phosphatidylinositol 5-phosphate. Binds with high affinity to phosphatidylinositol 3,5-bisphosphate (PtdIns(3,5)P2) but also to phosphatidylinositol 3-phosphate (PtdIns(3)P), phosphatidylinositol 4-phosphate (PtdIns(4)P), and phosphatidylinositol 5-phosphate (PtdIns(5)P), phosphatidic acid and phosphatidylserine. Negatively regulates ER-Golgi protein transport (By similarity). Probably in association with MTMR9, plays a role in the late stages of macropinocytosis by dephosphorylating phosphatidylinositol 3-phosphate in membrane ruffles. Acts as a negative regulator of KCNN4/KCa3.1 channel activity in CD4(+) T-cells possibly by decreasing intracellular levels of phosphatidylinositol 3-phosphate. Negatively regulates proliferation of reactivated CD4(+) T-cells. In complex with MTMR9, negatively regulates DNA damage-induced apoptosis. The formation of the MTMR6-MTMR9 complex stabilizes both MTMR6 and MTMR9 protein levels.
Tractability: Small molecule: it has a binding pocket of medium quality. Antibody: UniProt places it where antibodies can reach, with high confidence; its Gene Ontology location is reachable by antibodies, with medium confidence. PROTAC: ubiquitination databases record sites on it; its protein half-life has been measured.
Gene: Protein-coding gene on chromosome 13 (25,245,495 to 25,287,521, reverse strand). Ensembl gene ENSG00000139505.
Subcellular location: Cytoplasm; Endoplasmic reticulum-Golgi intermediate compartment; Endoplasmic reticulum; Cell projection, ruffle membrane; Cytoplasm, perinuclear region
Pathways (Reactome):
Metabolism: Synthesis of PIPs at the plasma membrane
Gene Ontology:
Molecular function: phosphatidylinositol-3,5-bisphosphate 3-phosphatase activity; phosphatidylinositol-3,5-bisphosphate phosphatase activity; phosphatidylinositol-3-phosphate phosphatase activity; protein binding; protein serine/threonine phosphatase activity; protein tyrosine phosphatase activity
Biological process: phosphatidylinositol dephosphorylation; phosphatidylinositol biosynthetic process; protein dephosphorylation; phosphatidylinositol metabolic process
Cellular component: cytoplasm; endoplasmic reticulum; endoplasmic reticulum-Golgi intermediate compartment; nuclear envelope; cytosol; perinuclear region of cytoplasm; ruffle membrane
Genetic constraint (gnomAD): Loss-of-function variants: 40 observed, 65.1 expected, observed/expected ratio (o/e) 0.61, 90% interval 0.48 to 0.8. The upper end of that interval is the gene's LOEUF score, 0.8, which puts it in group 3 of 6, group 1 being the genes least tolerant of losing a copy. Missense variants: 540 observed, 646.6 expected, observed/expected ratio (o/e) 0.84, 90% interval 0.78 to 0.9. Synonymous variants: 212 observed, 223.16 expected, observed/expected ratio (o/e) 0.95, 90% interval 0.85 to 1.07.
Homologues: Orthologues: macaque MTMR6 (98% identical), chimpanzee MTMR6 (96% identical), dog MTMR6 (96% identical), rabbit MTMR6 (96% identical), guinea pig MTMR6 (92% identical), pig MTMR6 (90% identical), mouse Mtmr6 (90% identical), rat Mtmr6 (90% identical), tropical clawed frog mtmr6 (70% identical), zebrafish mtmr6 (70% identical), Drosophila melanogaster Mtmr6 (48% identical), Caenorhabditis elegans mtm-6 (42% identical), and 10 more. Paralogues in human: MTMR7 (59% identical), MTMR8 (55% identical), MTMR2 (34% identical), MTMR1 (33% identical), MTM1 (33% identical), MTMR3 (33% identical), MTMR4 (32% identical), MTMR9 (28% identical), SBF1 (28% identical), SBF2 (28% identical), MTMR10 (19% identical), MTMR12 (18% identical), and 1 more.
Diseases named in the same sentence as MTMR6 in open-access papers:
MTMR6 is named in the same sentence as 7 diseases in open-access papers, as found by Europe PMC text mining. Sharing a sentence is not in itself a finding about the gene and the disease. The quoted sentences say what the papers report.
large intestine cancer (1 paper, 2024).
ovarian tumor (1 paper, 2023). "MiR-506 also induced cell cycle arrest by targeting MTMR6 in ovarian tumor cells." (PMID 37051101, 2023).
cancer (2 papers, 2024 to 2025). A tumor composed of atypical neoplastic, often pleomorphic cells that invade other tissues. "Another study shows that miR-506-3p can target myotubularin-related protein 6 (MTMR6) to prevent cancer cells from proliferating in OC tissues, arresting the cells in the G0/G1 phase and thereby inducing apoptosis." (PMID 40248198, 2025).
MTMR6 also shares sentences with these, for which no sentence is quoted: melanoma (1 paper); Myotubular myopathy (1); Neurodevelopmental delay (1); oral squamous cell carcinoma (1).